CSAG1 (chondrosarcoma associated gene 1)
Description:
May play an important role in maintaining centrosome integrity during mitosis.
Synonyms: CT24.1; CSAGE
Tractability: Antibody: UniProt predicts a signal peptide or a membrane-spanning region.
Gene: Protein-coding gene on chromosome X (152,727,484 to 152,733,736, reverse strand). Ensembl gene ENSG00000198930.
Subcellular location: Cytoplasm, cytoskeleton, microtubule organizing center, centrosome; Cytoplasm, cytoskeleton, spindle pole
Gene Ontology:
Biological process: centrosome cycle
Cellular component: centrosome; spindle pole
Homologues: Paralogues in human: CSAG2 (85% identical), CSAG3 (83% identical).
Diseases named in the same sentence as CSAG1 in open-access papers:
CSAG1 is named in the same sentence as 8 diseases in open-access papers, as found by Europe PMC text mining. Sharing a sentence is not in itself a finding about the gene and the disease. The quoted sentences say what the papers report.
breast carcinoma (2 papers, 2021 to 2023). "MAGEA1/3/12/13, MMP11/13, PRAC2, CSAG1, COL10/11A1 genes are overexpressed in breast cancer samples from patients with PP." (PMID 36675137, 2023).
hepatocellular carcinoma (1 paper, 2021). A malignant tumor that arises from hepatocytes. "CSAG1 and CSAG3 were representative factors for the alcohol-induced hepatocellular carcinoma, which implies that the results of the present study using capillaries were consistent with the in vivo findings." (PMID 34066517, 2021).
melanoma (1 paper, 2020). A malignant, usually aggressive tumor composed of atypical, neoplastic melanocytes. "Several of the CTAg genes detected in the CoMMpass analysis (MAGEA3, A6, A12, and CSAG1) were also in the CTAg gene set associated with resistance to anti-CTLA-4 therapy in melanoma." (PMID 32133047, 2020).
cancer (4 papers, 2019 to 2023). A tumor composed of atypical neoplastic, often pleomorphic cells that invade other tissues. "Examples of biclusters from this category include the biclusters consisting of genes from the Cancer-Testis antigens family—MAGEA2, MAGEA3, MAGEA6, MAGEA10, CSAG1, CSAG2, CSAG3 (Xq28)/CT45A3, CT45A5, CT45A6 (Xq26.3)." (PMID 31216036, 2019). "PRAC gene is normally expressed in the gastrointestinal tract, prostate, testis, urinary bladder, vagina, and placenta but not in breast tissue and, similarly, CSAG1 expression should be limited to brain and testis tissues, thus, their expression in breast tissues, is highly indicative of cancer." (PMID 36675137, 2023). "As a result, seven DEGs correlated with more than 10 TR-DDR genes (r>0.3) in at least 10 cancers were regarded as candidate genes, including COL2A1 (the R ranged from 0.39 to 0.60), MAGEA4 (0.24–0.62), FCRL4 (0.33–0.62), ZIC1 (0.24–0.33), LCN15 (0.20–0.41), PRSS3 (0.24–0.35), CSAG1 (0.31–0.38)." (PMID 36081518, 2022).
CSAG1 also shares sentences with these, for which no sentence is quoted: tumor (3 papers); colon cancer (2); chondrosarcoma (1); rectal cancer (1).